BCO2 (beta-carotene oxygenase 2)
Description:
Broad specificity mitochondrial dioxygenase that mediates the asymmetric oxidative cleavage of carotenoids. Cleaves carotenes (pure hydrocarbon carotenoids) such as all-trans-beta-carotene and lycopene as well as xanthophylls (oxygenated carotenoids) such as zeaxanthin, lutein and beta-cryptoxanthin at both the 9,10 and the 9',10' carbon-carbon double bond. Through its function in carotenoids metabolism regulates oxidative stress and the production of important signaling molecules.
Synonyms: BCDO2; FLJ34464; B-DIOX-II
Tractability: PROTAC: ubiquitination databases record sites on it.
Gene: Protein-coding gene on chromosome 11 (112,175,472 to 112,225,877, forward strand). Ensembl gene ENSG00000197580.
Subcellular location: Mitochondrion
Pathways (Reactome):
Sensory Perception: Retinoid metabolism and transport
Gene Ontology:
Molecular function: oxidoreductase activity, acting on single donors with incorporation of molecular oxygen, incorporation of two atoms of oxygen; 9,10 (9', 10')-carotenoid-cleaving dioxygenase activity; beta,beta-carotene-9',10'-cleaving oxygenase activity; beta-carotene 15,15'-dioxygenase activity
Biological process: carotene catabolic process; carotene metabolic process; carotenoid metabolic process; lutein catabolic process; lycopene catabolic process; regulation of mitochondrial membrane potential; regulation of reactive oxygen species metabolic process; retinal metabolic process; retinoic acid metabolic process; xanthophyll catabolic process; zeaxanthin catabolic process; isoprenoid metabolic process
Cellular component: mitochondrial matrix; mitochondrion
Genetic constraint (gnomAD): Loss-of-function variants: 44 observed, 54.03 expected, observed/expected ratio (o/e) 0.81, 90% interval 0.64 to 1.05. The upper end of that interval is the gene's LOEUF score, 1.05, which puts it in group 4 of 6, group 1 being the genes least tolerant of losing a copy. Missense variants: 593 observed, 633.8 expected, observed/expected ratio (o/e) 0.94, 90% interval 0.87 to 1. Synonymous variants: 206 observed, 224.09 expected, observed/expected ratio (o/e) 0.92, 90% interval 0.82 to 1.03.
Homologues: Orthologues: macaque BCO2 (92% identical), chimpanzee BCO2 (87% identical), dog BCO2 (80% identical), rabbit BCO2 (79% identical), guinea pig BCO2 (76% identical), pig BCO2 (75% identical), mouse Bco2 (75% identical), rat Rps13 (74% identical), tropical clawed frog bco2l (54% identical), zebrafish bco2b (54% identical), tropical clawed frog bco2 (52% identical), zebrafish bco2a (52% identical), and 2 more. Paralogues in human: RPE65 (38% identical), BCO1 (36% identical).
Diseases named in the same sentence as BCO2 in open-access papers:
BCO2 is named in the same sentence as 20 diseases in open-access papers, as found by Europe PMC text mining. Sharing a sentence is not in itself a finding about the gene and the disease. The quoted sentences say what the papers report.
diabetes mellitus (2 papers, 2024 to 2025). A metabolic disorder characterized by abnormally high blood sugar levels due to diminished production of insulin or insulin resistance/desensitization. "HSDL2, BCO2, CORIN, and SNORA80E may regulate cardiomyocyte cuproptosis in patients with diabetes mellitus-associated heart failure through effects on the immune system." (PMID 38883603, 2024). "Finally, we analyzed the relationships of the expression of the key genes (HSDL2, BCO2, CORIN, and SNORA80E) with that of transcription factors and regulatory genes in samples from patients with diabetes-associated heart failure." (PMID 38883603, 2024).
hepatocellular carcinoma (2 papers, 2021 to 2025). A malignant tumor that arises from hepatocytes. "BCO2 is a mitochondrial enzyme that converts zeaxanthin into apocarotenoids and has been shown to be upregulated by oxidative stress in liver carcinoma cells." (PMID 40427457, 2025).
vitamin A deficiency (2 papers, 2017 to 2018). Deficiency of vitamin A due to malnutrition, malabsorption, or dietary lack. "Overall, using the well-studied Rbp4−/− mouse model of vitamin A deficiency, we found that BCO2 deficiency exacerbated embryonic retinol deficiency and the associated malformations." (PMID 29892071, 2018). "Interestingly, our experiments demonstrated that BCO2 deficiency exacerbated embryonic vitamin A deficiency." (PMID 29892071, 2018).
atherosclerosis (1 paper, 2015). A disease characterized by the build-up of fatty material and calcium deposition in the arterial wall resulting in partial or complete occlusion of the arterial lumen. "Three of the genes also exhibited significant eQTL in aorta; Nnmt (p = 1.01×10−11), Bco2 (p = 1.61×10−4), 1110032A03Rik (p = 2.18×10−4), and their expression levels were correlated with atherosclerosis (r = 0.26–0.39, p = 2.6×10−2–6.4×10−4)." (PMID 26694027, 2015).
breast carcinoma (1 paper, 2018). "To determine if lutein-induced ROS production in breast cancer cells is dependent on the expression of BCO2, we analyzed BCO2 protein expression in normal and breast cancer cell lines by western blot." (PMID 29662002, 2018). "However, in contrast to prostate cancer, we now show that BCO2 expression in breast cancer cells is even greater than that in normal breast epithelial cells, which suggests that the observed lutein-mediated increase in ROS generation may not be BCO2-dependent in breast cancer." (PMID 29662002, 2018).
lung carcinoma (1 paper, 2023). "However, future human intervention studies are needed to identify role of BCO1/BCO2 genotypes in lung cancer development and establish dietary recommendations for carotenoids." (PMID 36771049, 2023).
prostate carcinoma (1 paper, 2018). A carcinoma that arises from epithelial cells of the prostate gland. "We previously determined that BCO2 is highly expressed in normal prostatic epithelial cells, but its expression is decreased and even lost in many prostate cancer cell lines and tissues." (PMID 29662002, 2018).
renal dysfunctions (1 paper, 2023). "Hence, we concluded that the natural carotenoid, i.e., BC can be used for the management of uremic toxin (IS)-induced renal dysfunctions due to its multi-targeted actions, including BCO2 activation." (PMID 37893028, 2023).
cancer (2 papers, 2018 to 2021). A tumor composed of atypical neoplastic, often pleomorphic cells that invade other tissues. "The difference in terms of the observed anti-cancer outcome suggested that BCO2 expression may cause a difference in terms of the pathway taken to exhibit anti-cancer property." (PMID 34202203, 2021). "Conversely, bco2 gene expression is decreased in several cancers." (PMID 29662002, 2018).
infection (2 papers, 2020 to 2025). The state of being infected such as from the introduction of a foreign agent such as serum, vaccine, antigenic substance or organism. "Together, enhanced IRF3 activation at baseline and improved survival rates supported a model in which BCO2 deficiency establishes an infection-ready lung state." (PMID 41228402, 2025).
metabolic disorder (2 papers, 2017 to 2023). "Collectively, these results indicate that ablation of BCO2 leads to metabolic disorder, which might be caused by dysregulated mitochondrial function." (PMID 29116185, 2017).
tumor (1 paper, 2019). "AI cells express lower levels of the lycopene metabolizing enzyme, BCO2, which assists in inhibiting tumor promoting NF-κB signaling, independent of its lycopene metabolizing function." (PMID 30875962, 2019).
BCO2 also shares sentences with these, for which no sentence is quoted: Alzheimer disease (1 paper); diabetic cardiomyopathy (1); endocrinopathies (1); heart failure (1); Hepatic steatosis (1); Hyperglycemia (1); Infertility (1); microphthalmia (1).